ZNF701 (zinc finger protein 701)
Description:
May be involved in transcriptional regulation.
Synonyms: FLJ10891
Tractability: PROTAC: UniProt records ubiquitination sites on it; ubiquitination databases record sites on it.
Gene: Protein-coding gene on chromosome 19 (52,555,822 to 52,599,928, forward strand). Ensembl gene ENSG00000167562.
Subcellular location: Nucleus
Subcellular location (Human Protein Atlas): Nucleoplasm; Centriolar satellite
Pathways (Reactome):
Gene expression (Transcription): Generic Transcription Pathway
Gene Ontology:
Molecular function: DNA-binding transcription factor activity, RNA polymerase II-specific; RNA polymerase II cis-regulatory region sequence-specific DNA binding
Biological process: regulation of transcription by RNA polymerase II; regulation of DNA-templated transcription
Cellular component: nucleus
Genetic constraint (gnomAD): Loss-of-function variants: 5 observed, 4.09 expected, observed/expected ratio (o/e) 1.22, 90% interval 0.61 to 1.89. That is too few expected variants to judge how well the gene tolerates losing a copy. Missense variants: 528 observed, 547.55 expected, observed/expected ratio (o/e) 0.96, 90% interval 0.9 to 1.04. Synonymous variants: 161 observed, 185.41 expected, observed/expected ratio (o/e) 0.87, 90% interval 0.76 to 0.99.
Homologues: Orthologues: chimpanzee ZNF701 (98% identical), macaque ZNF701 (84% identical). Paralogues in human: ZNF888 (82% identical), ZNF813 (73% identical), ZNF468 (72% identical), ZNF525 (72% identical), ZNF761 (72% identical), ZNF765 (71% identical), ZNF578 (70% identical), ZNF860 (69% identical), ZNF816 (65% identical), ZNF766 (51% identical).
Diseases named in the same sentence as ZNF701 in open-access papers:
ZNF701 is named in the same sentence as 2 diseases in open-access papers, as found by Europe PMC text mining. Sharing a sentence is not in itself a finding about the gene and the disease.
ZNF701 shares sentences with these, for which no sentence is quoted: asthma (1 paper); Sepsis (1).